INS (insulin)
Diseases named in the same sentence as INS in open-access papers (continued):
Sharing a sentence is not in itself a finding about the gene and the disease.
Hypoglycemia (continued). "Further studies are required to determine if the better option is to provide a second glucose load at the time of peak hypoglycemia, or to reduce the dose of IV insulin." (PMID 33328554, 2020). "Methotrexate with hydroxychloroquine helped reduce the severity of autoimmunological symptoms with concurrent decrease in the concentration of fasting insulin and reduction of hypoglycaemia episodes." (PMID 32755965, 2020). "Subsequently, skeletal muscle and the kidneys are key tissues that clear blood insulin via tissue-mediated insulin uptake and enzymatic degradation, which can protect against excessive insulin load and hypoglycemia." (PMID 32860984, 2020). "Major populations of neuropeptide Y (NPY)-expressing neurons are located in the arcuate nucleus, with another in the nearby lateral hypothalamus that intrinsically sense extracellular glucose and respond to insulin-induced hypoglycemia." (PMID 32193527, 2020). "Across baseline insulin regimen subsets, reported hypoglycemia (<70 mg/dl) at baseline vs. at study completion, respectively, was 23% vs. 19% for the basal only cohort; 46% vs. 33% for the basal-bolus cohort; and 38% vs. 23% for the premix cohort." (PMID 33202616, 2020). "While fasting, the insulin response is mitigated by glucagon, glucocorticoids and catecholamines in order to prevent insulin-induced hypoglycemia." (PMID 32872570, 2020). "In hypoglycemia, increasing sympathetic nerve activity promotes liver glucose production, reduced insulin secretion, and increased glucagon secretion." (PMID 33817219, 2020). "The adrenal axis was evaluated by measuring plasma cortisol at baseline and following insulin-induced hypoglycemia." (PMID 33117295, 2020). "It is possible that the mild–moderate exercise regimen, leads through stimulus ‘generalisation’, to suppression of the subsequent counterregulatory response to insulin-induced hypoglycaemia." (PMID 31942669, 2020). "Our study found that the incidence of hypoglycemia in hospitalized patients with T2DM with intensive insulin therapy was 51.0%." (PMID 33015194, 2020). "Understanding the risk of abrupt reduction in HbA1c, as well as the potential moderating influence of hypoglycemia and glucose variability, will become increasingly important as we approach the era of closed-loop insulin delivery." (PMID 33132212, 2020). "A low insulin dose protocol (4 mU/kg/min) was used, as in, to minimize direct inhibitory effects of insulin on ghrelin secretion in WT mice, while still achieving hypoglycemia." (PMID 33042003, 2020). "Mild hypoglycemia that occurs when the insulin dose continues to decrease indicates a long-term drug-free euglycemic remission." (PMID 32149152, 2020). "The insulin level at the time of hypoglycemia had the highest AUC of 0.866 (95% CI 0.771–0.962, p < 0.001) compared to the amino acid and acylcarnitine levels." (PMID 33133020, 2020). "CHI was diagnosed in 278 individuals based on inappropriately detectable insulin and/or C-peptide measurements at the time of hypoglycaemia which persisted beyond 6 months of age." (PMID 32027664, 2020). "In a systematic review, insulin was reported to have higher rates of neonatal hypoglycemia than metformin." (PMID 33403188, 2020). "The biochemical diagnosis of an insulinoma requires inappropriate insulin secretion in the presence of unequivocal hypoglycemia." (PMID 32605595, 2020). "Abnormal cardiac repolarization during hypoglycemia appears to be mediated by both the direct effect of sympathoadrenal stimulation and catecholamine- and insulin-induced hypokalemia on cardiac ion channels." (PMID 33374113, 2020). "Hypoglycemia is a side effect that is especially likely to occur in diabetics who control blood sugar with oral hypoglycemic agents or insulin." (PMID 32774458, 2020). "As insulin-induced hypoglycemia elevated ARC POMC neuronal activity, this ARCPOMC → DMVACh → liver circuit that we identified would plays a critical role in the counterregulatory response to hypoglycemia." (PMID 33293550, 2020).
Hypoglycemia (continued). "The prediction model will eventually help to automatically control the amount of insulin according to hypoglycemia, hyperglycemia, and nocturnal glucose." (PMID 33198170, 2020). "Herein, we investigated the use of diffuse correlation spectroscopy (DCS) to monitor the dynamics of CBF during insulin-induced hypoglycemia in adults." (PMID 33277531, 2020). "Both groups agreed that weight gain, hypoglycemia, and embarrassment about having to take insulin were barriers to its use." (PMID 32957991, 2020). "For many years, glucagon has been thought of as the counterregulatory hormone to insulin with a primary function of increasing blood glucose concentrations and protecting against hypoglycemia." (PMID 33333850, 2020). "We therefore tested how microglial surveillance of the brain parenchyma is affected by a glucose decrease in an insulin-induced hypoglycemia in vivo model." (PMID 32214088, 2020). "As an alternative (or complement) to basal insulin-dose reduction, simple carbohydrate consumption (up to 70–90 g/h) during prolonged aerobic activities can help prevent hypoglycaemia and support performance." (PMID 32533229, 2020). "The characteristics of insulin autoimmune syndrome are the combination of fasting hypoglycemia, a high concentration of total immunoreactive insulin, and the presence of AA to native human insulin in sera." (PMID 32481667, 2020). "In a study by Lee and cols., fasting blood glucose was found to be the most important determinant of the dose of insulin required to achieve adequate biochemical hypoglycemia (blood glucose < 2.2 mmol/l) during an ITT." (PMID 32187262, 2020). "Although the insulin dose was carefully titrated, patients experienced 0.21 ± 0.22 mild hypoglycemia and 0.02 ± 0.04 moderate hypoglycemia episodes per day during the 2~3 weeks of CSII therapy." (PMID 32149152, 2020). "This simulator also includes models for CGM measurement noise, insulin sensitivity variations, subject-specific rescue carbohydrate, and hypoglycemia unawareness." (PMID 32517068, 2020). "A total of 281 patients (90.1% hypoglycemia cases versus 82.8% in control) were given insulin during their hospital stay (P-value 0.054)." (PMID 32133264, 2020). "Severe hypoglycemia was also found to occur more often with intensive insulin management (6.8% vs. 0.5%, P<0.001)." (PMID 33118731, 2020). "This is consistent with prior studies showing correlation between blood glucose and sickness behavior and others showing that insulin-induced hypoglycemia suppresses social activity in c57BL/6 mice." (PMID 32513828, 2020). "The most commonly performed testing involves the measurement of plasma insulin and C-peptide levels during hypoglycemia (serum glucose less than 2.8 mmol/L), typically in the setting of a supervised inpatient 72-hour fast." (PMID 32605595, 2020). "Modulating the ATP-sensitive potassium channels of the beta cell through medical treatment with diazoxide in conjunction with glucagon, octreotide and/or nifedipine are some of the options to inhibit insulin secretion and in turn, control the hypoglycemia." (PMID 33108363, 2020). "Mice with a CRTC2 defect showed hypoglycemia and maintained better insulin sensitivity when fed a HFD, and the mRNA expression of gluconeogenic genes was significantly decreased in the liver." (PMID 32020874, 2020). "In contrast to these transporters, GLUT4 located in intracellular vesicles on the periphery through hypoglycemia trigger the hunger mechanism coupled with food acquisition by stimulating insulin release, so that energy and body mass remain in balance." (PMID 32121669, 2020). "HH will demonstrate detectable C-peptide or insulin in the face of hypoglycemia, with simultaneously low/undetectable alternative substrates (ketones and fatty acids)." (PMID 32185602, 2020).
Hypoglycemia (continued). "The higher rates of severe hypoglycaemic events in the insulin-experienced population of CONCLUDE, who had at least one hypoglycaemia risk factor (including a history of severe hypoglycaemia), permitted an evaluation of these events." (PMID 31984443, 2020). "The most commonly used secretagogues include insulin-induced hypoglycemia [insulin tolerance test (ITT)], arginine [arginine stimulation test (AST)], clonidine, glucagon, levodopa, and growth hormone releasing hormone (GHRH)." (PMID 33362716, 2020). "Of the 61 included samples from CHI patients, four samples were included from patients with p-insulin >55 pmol/L during hypoglycemia despite ongoing treatment with octreotide." (PMID 33679602, 2020). "A more recent study conducted in patients with T1D and hypoglycemia unawareness reported that the use of SAP with low glucose suspend (LGS) function significantly reduced the incidence of severe hypoglycemia, compared to standard insulin pump therapy." (PMID 33153229, 2020). "A reduction in dextrose load risks compromised nutritional intake, while insulin therapy can lead to hypoglycaemia." (PMID 31399480, 2020). "A retrospective analysis of a large cohort of individuals with T1D on continuous subcutaneous insulin infusion pointed to a higher prevalence of cardiovascular disease in those with repeated severe hypoglycemia." (PMID 30781593, 2019). "To test this, we used an animal model of insulin-induced hypoglycemia and injected DCA (100 mg/kg, i.v., two days) following hypoglycemic insult." (PMID 31052436, 2019). "The elevated incidence of hypoglycemia with SU therapy is related to its mode of action, which involves stimulation of insulin release from pancreatic beta cells that occurs independently of plasma glucose levels." (PMID 30876392, 2019). "Alamoudi recently reported similar outcomes in those on CSII compared to those on MDI using analog insulin preparations during Ramadan fasting, though severe hypoglycaemia was reported in 1.3%." (PMID 31866948, 2019). "In another literature study, physical activity data were used to enhance the performance of an algorithm for basal insulin suspension in mitigation of exercise-induced hypoglycemia." (PMID 30922295, 2019). "After an initial bolus of intravenous (IV) 0.9% normal saline, the patient was started on a continuous IV infusion of insulin with a second infusion of 5% dextrose and sterile water added to prevent hypoglycemia." (PMID 31488052, 2019). "Better hypoglycemia accuracy will be especially useful for insulin-dependent patients who need accurate glucose readings for proper dosing." (PMID 31757994, 2019). "This stems from fear of insulin self-injection, dose adjustments, weight gain, hypoglycemia, and fear of advanced disease and hence more complications." (PMID 30775378, 2019). "Evidence suggests that insulin is beneficial for peripheral nervous system (PNS) function and serves a promoter of axonal regeneration after injury, whereas hypoglycemia during normal insulin levels causes axonal degeneration in the PNS." (PMID 31356602, 2019). "Laboratory tests revealed hypoglycemia (blood glucose: 2.5 mmol/L) HI (plasma insulin level: 5.9 μIU/mL) when she had an episode." (PMID 31208162, 2019). "Inappropriate insulin secretion can suppress the production of ketone bodies, which serve as an alternative fuel during hypoglycemia." (PMID 31208162, 2019). "Secondary outcomes included severe hypoglycemia and change of serum potassium after insulin administration." (PMID 30890150, 2019). "Compared with that of the insulin group, the weekly combinational therapy group had less incidence of hypoglycemia." (PMID 31950036, 2019). "When eating only meat, GIP presumably allows the insulin levels to rise enough to store the fat and protein and the glucagon levels to rise enough to prevent hypoglycemia." (PMID 31781045, 2019).
Hypoglycemia (continued). "Signs/symptoms and abnormalities in labs indicating hypoglycemia were more prevalent in patients with the interaction aspirin + insulin and prescribed with high doses of the insulin." (PMID 31349877, 2019). "The patient’s clinical manifestations, hypoglycemia, insulin/blood glucose > 0.4, pancreatic enhancement CT, and upper abdominal enhanced MRI results supported the diagnosis of an islet cell tumor." (PMID 32009878, 2019). "Such a response is triggered during an IMIVGTT as a result of administration of insulin, which can induce hypoglycaemia in healthy insulin-sensitive patients." (PMID 31829209, 2019). "It has also been reported that insulin can be added to the sugar-containing liquid, but the blood glucose level should be closely monitored to prevent the occurrence of hypoglycemia, and the recommended monitoring time is 24 to 72 hours." (PMID 31593098, 2019). "Four devices were implanted in each of two rats (eight devices total) and tested for 5 days at the end of which the animals were sacrificed at the end of insulin-induced severe hypoglycemia within glucose and insulin tolerance test." (PMID 31757994, 2019). "In 2 retrospective studies, similar potassium-lowering effects were found with the administration of either 5 or 10 U of insulin (and 25 g of dextrose), but a higher incidence of hypoglycemia occurred with the higher insulin dose." (PMID 30820692, 2019). "The present study examined the treatment effect of intensification with DPP4i, insulin, or TZD on the risk of severe hypoglycemia (SH), CVD, and all-cause mortality among patients with T2DM on Met-SU dual therapy." (PMID 31877127, 2019). "Coinfusion of insulin and naloxone during antecedent hypoglycemia in human studies improved the epinephrine response, endogenous glucose production, and hypoglycemia symptom scores after subsequent hypoglycemia." (PMID 31013147, 2019). "Fewer Gla‐300 switchers experienced hypoglycaemia at 3‐ and 6‐month follow‐up (Gla‐300 switchers vs other basal insulin switchers: 3 m, 4.4% vs 8.4%, P < 0.001; 6 m, 6.0% vs 11.4%, P < 0.001)." (PMID 31294087, 2019). "The initiation and intensification of insulin regimens is often hampered by hypoglycaemia and the fear of hypoglycaemia." (PMID 31796048, 2019). "Unfortunately, the use of synthetic insulin and oral glucose-lowering drugs have many side effects such as severe hypoglycemia at high doses, neurological disturbances, hepatic injury, headache, digestive disorder, lactic acidosis, and perhaps death." (PMID 30937310, 2019). "Research has also demonstrated that the omission of pre-exercise bolus, but continuation of basal insulin dosages offers a protective effect against the occurrence of hypoglycaemia during and soon after a fasted bout of morning RE." (PMID 31428047, 2019). "Prescriptions for longer-acting insulin analogs, or insulin degludec can prevent hypoglycemia during unpredictable food supply periods." (PMID 31693702, 2019). "In a randomized controlled trial, bihormonal pump therapy was compared with insulin only pump therapy showing improvement in mean blood glucose and reduction in incidence of hypoglycemia." (PMID 30875898, 2019). "Glucagon, the insulin counter regulatory hormones plays an important role in preventing hypoglycemia, particularly when the body receives an insulin-stimulating agent under fasting conditions." (PMID 31404283, 2019). "As insulin was appropriately suppressed in one patient in our cohort and was not measured in three further individuals we cannot be certain that hypoglycaemia results from dysregulated insulin secretion in all cases with a 9p deletion." (PMID 32832699, 2019). "The insulin-loaded starch NP formulation that contained permeation enhancers demonstrated sustained hypoglycemia for up to 6 h." (PMID 31443473, 2019).
Hypoglycemia (continued). "Extant research in patients with gastroparesis demonstrated the potential benefits of prokinetic drugs in accelerating GE and in reducing hypoglycemia due to the mismatch between exogenous insulin and PP glucose levels." (PMID 31295897, 2019). "One of the few blinded ED studies of hyperkalemia management found a 17% rate of clinically significant hypoglycemia after insulin–dextrose therapy." (PMID 30820692, 2019). "Hypoglycemia, which is defined as a blood glucose concentration of less than 70 mg/dL, is considered as a common acute complication of insulin therapy." (PMID 31651281, 2019). "Reducing parenteral intake risks compromised nutritional delivery, while insulin infusions can lead to hypoglycaemia." (PMID 30232094, 2019). "For patients with hypoglycemia, increases in blood glucose levels can promote endogenous insulin production, and insulin can reverse ketogenesis." (PMID 31593098, 2019). "In insulin induced hypoglycemia stress test, indomethacin intake resulted in increased ACTH and decreased cortisol levels, while in case of ASA administration, ACTH levels decreased and cortisol levels remained unaltered." (PMID 31534960, 2019). "Neonatal hypoglycemia was included as an outcome between metformin and insulin by 15 studies which involved 2755 GDM patients." (PMID 31781670, 2019). "Consistent with the data from the insulin-induced hypoglycemia model, the ArcPomc−/− mice had impaired responses to 2-DG-induced glucopenia." (PMID 30503832, 2019). "We subjected WT and weight-matched ArcPomc−/− mice to hypoglycemia induced by a high dose of insulin (2 U/kg, ip)." (PMID 30503832, 2019). "This approach also resulted in unacceptably high hypoglycaemia rates of 9.5% (compared with 0% in our PP analysis), presumably due to a cumulative effect of administered insulin." (PMID 30737563, 2019). "Because of earlier peak and faster clearance, inhaled insulin has been shown to reduce the risks of hypoglycemia and also able to achieve comparable glycemic control with basal insulin." (PMID 31470605, 2019). "The major side effect of insulin is hypoglycemia, which has been reported to occur up to 75% in subjects, depending of the protocol." (PMID 30820692, 2019). "In the repeated-hypoglycemia group (n = 4), BG levels 2 h after injection of insulin were significantly reduced from the matched preinjection time points: 3.1 ± 0.1 mM (day 1), 2.8 ± 0.2 mM (day 2), and 2.7 ± 0.1 mM (day 3)." (PMID 31013147, 2019). "The commercial MiniMed 640G system was assessed in a single-arm outpatient study, a single-arm inpatient study with nocturnal hypoglycemia induced by increased insulin delivery, and a randomized controlled trial conducted in children and adolescents." (PMID 30922295, 2019). "Overnight fasting and insulin induced-hypoglycemia resulted in coexpression c-FOS and OREXIN-A in perifornical part of the lateral hypothalamus." (PMID 30996341, 2019). "These include hypoglycemia and hyperglycemia alarms, digital log books, carbohydrate counters, and insulin dosing calculators." (PMID 31250124, 2019). "Hypoglycemia has been one of the many concerning side‐effects among patients receiving insulin, SU and glinides." (PMID 31486247, 2019). "We conducted a systematic review and meta-analysis of randomized controlled trials (RCTs) to assess the effects of short-acting insulin analogues vs regular human insulin on hypoglycemia and postprandial glucose in patients with T1DM." (PMID 30622653, 2019). "In a first proof-of-concept study in 2007, we used the insulin tolerance test and showed that copeptin measured during insulin-induced hypoglycemia remains low in patients with DI while increasing in patients with intact posterior pituitary function." (PMID 31067508, 2019). "The introduction of insulin analogues, with both rapid and prolonged durations of action, has been shown to reduce hypoglycemia and offer improved flexibility to patients." (PMID 31250124, 2019).